FGF13 (fibroblast growth factor 13)
Description:
Microtubule-binding protein which directly binds tubulin and is involved in both polymerization and stabilization of microtubules (By similarity). Through its action on microtubules, may participate in the refinement of axons by negatively regulating axonal and leading processes branching (By similarity). Plays a crucial role in neuron polarization and migration in the cerebral cortex and the hippocampus (By similarity). Regulates voltage-gated sodium channel transport and function. May also play a role in MAPK signaling (By similarity). Required for the development of axonal initial segment-targeting inhibitory GABAergic synapses made by chandelier neurons (By similarity).
Synonyms: FGF-13; FHF-2; FHF2; FGF2; FLJ30672; DEE90; LINC00889; XLID110
Tractability: Antibody: UniProt places it where antibodies can reach, with medium confidence; its Gene Ontology location is reachable by antibodies, with medium confidence. PROTAC: its protein half-life has been measured.
Gene: Protein-coding gene on chromosome X (138,614,727 to 139,222,777, reverse strand). Ensembl gene ENSG00000129682.
Subcellular location: Nucleus (Isoform 1); Cytoplasm (Isoform 2); Nucleus; Cytoplasm (Isoform 3); Cytoplasm (Isoform 4); Cytoplasm (Isoform 5); Cell projection, filopodium; Cell projection, growth cone; Cell projection, dendrite; Cell membrane, sarcolemma; Cytoplasm
Subcellular location (Human Protein Atlas): Cytosol
Pathways (Reactome):
Muscle contraction: Phase 0 - rapid depolarisation
Gene Ontology:
Molecular function: protein binding; sodium channel regulator activity; beta-tubulin binding; growth factor activity; microtubule binding; transmembrane transporter binding
Biological process: MAPK cascade; positive regulation of voltage-gated sodium channel activity; cell-cell signaling; cerebral cortex cell migration; establishment of neuroblast polarity; hippocampus development; inhibitory synapse assembly; learning; memory; microtubule polymerization; negative regulation of collateral sprouting; negative regulation of microtubule depolymerization; nervous system development; neurogenesis; neuron migration; protein localization to plasma membrane; regulation of cardiac muscle cell action potential involved in regulation of contraction; signal transduction; sodium ion transport
Cellular component: cytoplasm; cytosol; nucleus; axon; dendrite; filopodium; growth cone; intercalated disc; lateral plasma membrane; microtubule; neuron projection; plasma membrane; sarcolemma
Homologues: Orthologues: mouse Fgf13 (99% identical), rat Fgf13 (99% identical), zebrafish fgf13a (91% identical), zebrafish fgf13b (72% identical). Paralogues in human: FGF14 (58% identical), FGF11 (53% identical), FGF12 (50% identical), FGF9 (27% identical), FGF20 (25% identical), FGF16 (25% identical), FGF4 (24% identical), FGF10 (24% identical), FGF18 (24% identical), FGF5 (24% identical), FGF3 (23% identical), FGF6 (23% identical), and 9 more.
Diseases named in the same sentence as FGF13 in open-access papers:
FGF13 is named in the same sentence as 75 diseases in open-access papers, as found by Europe PMC text mining. Sharing a sentence is not in itself a finding about the gene and the disease. The quoted sentences say what the papers report.
epilepsy (12 papers, 2019 to 2025). A brain disorder characterized by episodes of abnormally increased neuronal discharge resulting in transient episodes of sensory or motor neurological dysfunction, or psychic dysfunction. "Conversely, a maternally transmitted chromosomal translocation that disrupts the X-linked FGF13 locus and eliminates FGF13-VY expression while preserving expression of FGF13-S causes a seizure disorder in two brothers." (PMID 39773461, 2025). "To determine how FGF13 affects neuronal excitability and provide insight into how FGF13 variants contributes to seizure disorders, we developed genetic mouse models that eliminate Fgf13 in specific neuronal cell types." (PMID 38659789, 2024). "Point mutations in FGF12 and FGF13 (aka FHF1 and FHF2) cause epilepsy and intellectual disability." (PMID 40662358, 2025). "Similarly, mutations in genes involved in synaptic targeting by ChCs onto the AISs of pyramidal neurons including L1CAM, ERBB4, and FGF13 have been implicated in epilepsy, schizophrenia or intellectual disability." (PMID 34630048, 2021). "Both LGI2 and FGF13 mutations are implicated in syndromes with epilepsy as a component." (PMID 31297048, 2019). "LGI2 and FGF13 dysfunction have also been linked to epilepsy." (PMID 31297048, 2019). "In a genetic epilepsy family associated with cognitive impairment, a chromosome translocation disrupts FGF13 and reduces the expression of FGF13, which are speculated to cause enhanced excitability within local circuits of hippocampus, thereby resulting in the clinical phenotype of epilepsy." (PMID 34184986, 2021). "Understanding the molecular mechanisms that drive the pathogenesis of Fgf13-related seizures will enhance our understanding of DEEs and epilepsy at large." (PMID 38659789, 2024). "Indeed, individuals with a LOF SNV in SCN8A/SCN2A, the genes encoding NaV1.6/NaV1.2, also exhibit epilepsy, and the concept that impaired inhibitory neuronal excitability results in epilepsy has been considered in the related disorder of FGF13, a member of the FGF homologous factor family." (PMID 37286232, 2023). "In addition, FGF13 mutant mice exhibit an imbalance in excitatory and inhibitory synaptic input activity within the local hippocampal circuit, leading to a clinical phenotype of epilepsy." (PMID 38907070, 2025).
breast carcinoma (9 papers, 2013 to 2021). "High expression of one of these genes, Fgf13, is associated with early human breast cancer metastasis in a clinical dataset." (PMID 31341204, 2019). "In the combined analysis of all samples, the minor allele of rs619373, located in FGF13 (Xq26.3), was associated with higher breast cancer risk (HR = 1.30, 95% CI 1.17–1.45, P = 3.1×10−6)." (PMID 23544012, 2013). "As an illustration, the authors validated in an external publicly available dataset a significant upregulation of fibroblast growth factor 13 (FGF13) in tissues of older breast cancer patients." (PMID 31535319, 2020). "High expression of FGF13 regulated by E2F1 transcription factor was reported to correlate with a shorter cell migration time to metastatic sites in breast cancer." (PMID 33298014, 2020). "Deletion of Fgf13 in a MMTV-PyMT breast cancer cell line reduces colonization of the lungs in a tail vein injection." (PMID 31341204, 2019). "Together, these results show that Fgf13 regulates breast cancer pulmonary colonization, a critical step in metastasis." (PMID 31341204, 2019). "Similarly, FGF13, which is highly expressed in cancers such as glioma, prostate cancer, and breast cancer, was found to be upregulated in male GB as compared to the female counterparts." (PMID 34621669, 2021). "Additionally, up-regulated FGF13 gene expression was identified in highly metastatic breast cancer cells." (PMID 33298014, 2020). "In addition, this analysis has also identified a new role for the E2F1 target gene fibroblast growth factor 13 (Fgf13) in breast cancer metastasis." (PMID 31341204, 2019). "High expression of Fgf13 was significantly associated with faster onset of distant metastasis across all cases of breast cancer but was not significant across all Er+ tumors." (PMID 31341204, 2019). "Besides FGF13 and VEGFD, the candidate CTAG2 is involved in cellular movement and has previously been associated with invasion in breast cancer." (PMID 30555413, 2018). "Together these data led to the hypothesis that Fgf13 is critical for breast cancer metastasis, and that upregulation of Fgf13 may partially explain how E2F1 promotes breast cancer metastasis." (PMID 31341204, 2019). "For the two SNPs associated with breast cancer with P<10−5, neither rs619373, located in FGF13 (Xq26.3), nor rs184577, located in CYP1B1-AS1 (2p22-p21), was associated with breast cancer risk in the general population or among BRCA1 mutation carriers." (PMID 23544012, 2013).
cervical cancer (8 papers, 2013 to 2021). A primary or metastatic malignant neoplasm involving the cervix. "Overexpression of Fgf13 is associated with shorter progression-free survival times in pancreatic cancer and poor outcome in cervical cancer." (PMID 33504014, 2021). "FGF13 is responsible for chemoresistance in cervical cancer, but this gene may be associated with drug resistance in BRCA." (PMID 31311202, 2019). "For example, FGF13, a representative of intracrine FGFs, has been found to contribute to the insensitivity of cervical cancer cells to cisplatin." (PMID 34830951, 2021). "A recent study demonstrated that FGF13 plays a pivotal role in mediating the resistance to platinum drugs in cervical cancer cells." (PMID 28114404, 2017). "Because HeLa cells were originally derived from cervical cancer, we analyzed the expression of FGF13 in biopsy samples obtained from cervical cancer patients before they received chemoradiotherapy using cisplatin." (PMID 24113164, 2013). "In preoperative cervical cancer biopsy samples from poor prognoses patients after cisplatin chemoradiotherapy, FGF13-positive cells were detected more abundantly than in the biopsy samples from patients with good prognoses." (PMID 24113164, 2013). "Thus the levels of FGF13 expression may serve as a useful guide when planning treatment for cervical cancer patients." (PMID 24113164, 2013).
glioma (6 papers, 2016 to 2022). A benign or malignant brain and spinal cord tumor that arises from glial cells (astrocytes, oligodendrocytes, ependymal cells). "Some studies have reported that FGF13 regulates glioma cell invasion and bevacizumab-induced glioma invasion." (PMID 35186111, 2022). "Although miR-504 was reported to inhibit cell proliferation and promote apoptosis in glioma, a low expression of FGF13 and miR-504 both indicate poor survival, suggesting that they are functionally synergistic." (PMID 34572448, 2021). "Previous studies indicated that FGF13 regulates GBM cell invasion and bevacizumab-induced glioma invasion." (PMID 33803224, 2021).
Intellectual disability (6 papers, 2014 to 2025). "Expressed in cortical neurons, Fgf13 is linked to X-chromosome-linked mental retardation in humans." (PMID 25374516, 2014). "A sum of 100 severe intellectual disability (ID) children (intelligence quotient [IQ] < 40) with detailed clinical histories were tested for the SNP of FGF13." (PMID 34184986, 2021). "In the human genome, miR-504 is an intronic miRNA, hosted by the fibroblast growth factor 13 gene (FGF13) on chromosome Xq26.3, which is highly expressed in the brain and was previously associated with Börjeson–Forssman–Lehmann syndrome, an X-linked mental retardation." (PMID 31861723, 2019).
Sepsis (5 papers, 2019 to 2023). Sepsis is defined as life-threatening organ dysfunction caused by a dysregulated host response to infection. "The identified FAM89A, FFAR3, G0S2, and FGF13 genes may help elucidate the molecular mechanisms underlying sepsis and drive the introduction of new biomarkers to advance diagnosis and treatment." (PMID 38050254, 2023). "Therefore, it appears likely that FFAR3, G0S2, and FGF13 participate in inflammation and metabolic reprogramming during sepsis." (PMID 38050254, 2023). "The interaction maps for the sepsis group show a similar pattern to those for SIRS, i.e., specific changes in the complement of genes associated with each hub gene and significantly increased stimulatory interactions for KLRK1, FGF13, and MYL9." (PMID 32318053, 2020). "In addition, there was association with FGF13 through BST1 and PCOLCE2 through SH3GLB1 in pediatric sepsis." (PMID 32318053, 2020). "FGF13 is also associated with TDRD9 in pediatric sepsis and no other hub entities in adult sepsis." (PMID 32318053, 2020). "In conclusion, the present study identified core immune‐related DEGs between severe burns and sepsis, including IL10, RETN, THBS1, FGF13, LCN2 and MMP9." (PMID 37060578, 2023). "Other biomarkers also correlate with outcome/prognosis e.g., CD177, FGF13, GRB10 and PPARG in both SIRS and sepsis." (PMID 38332914, 2023). "The majority of these clusters were not connected in most disease and control states, except for adult sepsis and adult SIRS with the gene clusters for TDRD9, CD177, GPR84, PCOLCE2, FGF13 and SLC16A3 interconnected at various points, either directly or through overlapped gene connections." (PMID 32318053, 2020).
cardiac hypertrophy (4 papers, 2023 to 2024). "Moreover, elevated FGF13 expression is associated with PO-induced hypertrophy, whereas deletion of FGF13 alleviates myocardial hypertrophy and cardiac function." (PMID 36871047, 2023). "Conversely, the fibroblast growth factor FGF13 was 3-fold repressed at T4 treatment, and this factor is a novel regulator of NF-κB which potentiates cardiac hypertrophy." (PMID 39285385, 2024). "FGF13 has been reported to be the most abundant FHF in the heart, which regulates heart hypertrophy signaling pathways, including the caveolae, and NF-κB pathways, so as to change cardiac hypertrophy." (PMID 38818580, 2024).
Cognitive impairment (4 papers, 2021 to 2025). Abnormal cognition is characterized by deficits in thinking, reasoning, or remembering. "Fgf13 deficiency in excitatory forebrain neurons is linked to neurodevelopmental delay and cognitive impairment, and excitatory neurons are hypothesized to be the relevant cell type for seizures in a DEE associated with FGF13 variants." (PMID 39773461, 2025). "Genetic disruption of FGF13 due to chromosome translocation in a genetic epilepsy family is also associated with cognitive impairment, in which not only the proband but also his mother’s maternal aunt together with her two children all exhibit cognitive impairments." (PMID 34184986, 2021). "Accumulating evidence suggests that overexpression of FGF13 enhances axonal regeneration and functional recovery by maintaining MT stabilization following spinal cord injury (SCI) and FGF13 deficiency causes cognitive impairment due to delayed neuron migration in both the cortex and hippocampus." (PMID 35295719, 2022).
Obesity (4 papers, 2011 to 2024). Accumulation of substantial excess body fat. "Recent studies have identified FGF13 as a new candidate gene for obesity, which regulates thermogenesis and energy balance." (PMID 36675322, 2023). "FGF13 heterozygous knockout mice presented impairment of the central nervous system’s sympathetic activation of brown fat, leading to obesity." (PMID 36675322, 2023). "A number of novel obesity candidate genes were also identified (Thbs1, Ppp1r3d, Tmepai, Trp53inp2, Ttc7b, Tuba1a, Fgf13, Fmr) that have inferred roles in fat cell function." (PMID 21915269, 2011).
prostate carcinoma (3 papers, 2018 to 2021). A carcinoma that arises from epithelial cells of the prostate gland. "The significantly upregulated genes in -CD82 cells such as CXCL14 and FGF13 could potentially serve as biomarkers or therapeutic targets for diagnosis and treatment of prostate cancer." (PMID 33298014, 2020). "In prostate cancer, FGF13 could act as an onco-switch and its expression was higher in malignant as well as locally invasive and metastatic cells when compared with benign control cells." (PMID 33298014, 2020). "High expression of FGF13 in metastatic prostate -CD82 cells observed in our study indicates a potential interaction between FGF13 and CD82 to promote metastasis in prostate cancer." (PMID 33298014, 2020).
BÖrjeson-Forssman-Lehmann syndrome (2 papers, 2019 to 2021). "Furthermore, deafness has been a common feature in patients with three main syndromes, the BÖrjeson-Forssman-Lehmann syndrome, Wildervanck syndrome, and Congenital Generalized Hirsutism, all of which are characterized by loss-of-function mutations in the Fgf13 gene." (PMID 34220452, 2021).
breast tumors (2 papers, 2021 to 2023). "Furthermore, FGF13 is highly upregulated in pancreatic endocrine and metastatic breast tumors, and FGF13 may enable cancer cells to avoid proteostasis stress induced by oncogene activation." (PMID 37108717, 2023).
cardiomyopathy (2 papers, 2024 to 2025). A disease of the heart muscle or myocardium proper. "Finally, Fgf13 is a novel regulator of NF-κB, and its expression is upregulated in cardiomyopathy." (PMID 39285385, 2024).
deafness (2 papers, 2021 to 2025). An inherited or acquired condition characterized by the complete loss of the ability to hear from one or both ears. "Recent studies also showed that patients with Wildervanck syndrome and congenital hypertrichosis carrying FGF13 functional deficiencies universally manifested deafness phenotype." (PMID 40617800, 2025). "In our study, 2-month-old Fgf13 cKO mice showed sensorineural deafness and mitochondrial apoptosis associated with SGN loss, but the temporal aspects of the loss were unclear." (PMID 34220452, 2021). "In this study, we found that selective deletion of Fgf13 in the inner ear of mice caused sensorineural deafness." (PMID 34220452, 2021). "Whether the deafness in these patients is caused by the loss function of Fgf13 and whether this gene plays any role in the auditory system is unknown." (PMID 34220452, 2021). "Whether the pathogenesis of deafness in these syndromic patients is associated with the Fgf13 mutation is unclear." (PMID 34220452, 2021). "Our data revealed a novel role for Fgf13 in the auditory system and suggest that the gene could be a potential candidate for understanding deafness." (PMID 34220452, 2021). "Together, this study reveals a novel role for Fgf13 in auditory function, and indicates that the gene could be a potential candidate for understanding deafness." (PMID 34220452, 2021). "In our study, Fgf13 knockout mice aged 8–12 weeks showed 30–47% SGN loss and elevated ∼40 dB of SPL at 4–32 kHz frequencies in the ABR test, which might provide new perspectives on the molecular mechanisms underlying SGN loss and deafness." (PMID 34220452, 2021). "Whether the pathogenesis of deafness in these syndromes is associated with the Fgf13 mutation is not known." (PMID 34220452, 2021).
fibrosis (2 papers, 2024 to 2025). the formation of excess fibrous connective tissue in an organ or tissue in a reparative or reactive process. "We first examined the alterations in collagen and FGF13 expressions in a TGFβ1-induced fibrosis modelin vitro." (PMID 38818580, 2024). "The results showed thatFgf13 knockdown inhibited ROCK1 protein upregulation by depolymerizing microtubules, indicating that ROCK is involved in FGF13 regulation in cardiac fibrosis via microtubules." (PMID 38818580, 2024). "Furthermore, FGF13 contributes to cardiac fibrosis via microtubule-dependent mechanisms." (PMID 40617800, 2025).
infertile (2 papers, 2018 to 2021). "Fgf13, one of the genes whose expression is decreased by SM, plays an important role in the reconstruction and degradation of the extracellular matrix in infertile aged women." (PMID 34091440, 2021). "First, the concentrations of FGF13 were examined in infertile patients after superovulation and not under normal physiological conditions." (PMID 30257687, 2018).
Insulin resistance (2 papers, 2019 to 2023). Increased resistance towards insulin, that is, diminished effectiveness of insulin in reducing blood glucose levels. "Corticotropin releasing hormone binding protein (CRHBP), ARHGEF15, MME, MAP1A, FGF13, and SHANK3 are novel biomarkers for the development of insulin resistance." (PMID 30678306, 2019).
lung adenocarcinoma (2 papers, 2024). A carcinoma that arises from the lung and is characterized by the presence of malignant glandular epithelial cells. "In tumorigenesis, fgf13 was found to be upregulated in lung adenocarcinoma patients and to be essential to the survival of cancer cells in vitro." (PMID 38791872, 2024). "FGF13 and PRKCB act as antioncogenes that inhibit tumor progression by modulating the immune functions in acute myeloid leukemia and lung adenocarcinoma." (PMID 38686055, 2024).